B3GALT5 (beta-1,3-galactosyltransferase 5)
Diseases named in the same sentence as B3GALT5 in open-access papers (continued):
Sharing a sentence is not in itself a finding about the gene and the disease.
type 1 diabetes (1 paper, 2018). "The changed expression of B3GALT5, B3GALT4 and B4GALT1 suggest that the development of type 1 diabetes is associated with changes in the composition of islet glycosphingolipids with increases in the neolacto/lacto series and decreased levels of gangliosides." (PMID 29671030, 2018).
ulcerative colitis (1 paper, 2024). An inflammatory bowel disease involving the mucosal surface of the large intestine and rectum. "Additionally, we observe a reduction in the expression of B3GALT5 and the Tn antigen, which indicates defective mucin O-glycan, in the colon tissue of patients with ulcerative colitis." (PMID 38733584, 2024).
cancer (16 papers, 2014 to 2025). A tumor composed of atypical neoplastic, often pleomorphic cells that invade other tissues. "In this study, molecular docking was carried out to explore the interaction between Ac-Gb4 and B3GALT5, which play a role in glycolipid synthesis associated with the cancer signaling pathway." (PMID 39769120, 2024). "It has been reported that expression of B3GALT5 is associated with cancer progression and can serve as cancer marker for diagnosis in gynecological cancers and prognosis in hepatocellular carcinoma." (PMID 33413566, 2021). "It appears responsible for efficient cancer-associated silencing and probably fine tissue-specific expression of a galactosyltransferase enzyme isoform (B3GALT5), which also underwent a particular evolutionary fate." (PMID 25256425, 2014). "B3GALT5-LTR is also involved in the synthesis of the cancer-associated glycan, sialyl Lewis a." (PMID 31936807, 2020). "Transcription of the B3GALT5 gene underwent a particular evolutionary fate, so that promoter hypermethylation, acting on one transcript, and hypomethylation of other sequences, acting on the other, cooperate on one gene to obtain full cancer-associated silencing." (PMID 25256425, 2014). "We here provided structuralinsights into the substrate specificityand possible reaction mechanisms of the β3GalT5-catalyzed reaction.This cancer-related enzyme plays a crucial role in glycolipid biosynthesisand demonstrates intriguing substrate preferences." (PMID 40130308, 2025). "First, we showed that AC displays a glycogene signature characterized by 42 glycogenes, where some of them, such as ALG11, ALG9, and B3GALT5, can be relevant for cancer patients." (PMID 34540372, 2021). "Even though there were multiple bands stained by mAb-A4 on Western blotting of hESC and cancer cell lysate, these bands were different proteins with the common glycan epitope because the B3GALT5 knockdown abolished Western blot binding." (PMID 28167527, 2017). "Therefore, B3GALT5 is the key enzyme producing these cancer-related glycans such as SSEA-3 and sialyl Lewis a." (PMID 31936807, 2020). "B3GALT5 transcription thus represents a promising model to address such novel issues, since hypomethylation of distant sequences, acting on the LTR transcript, and promoter hypermethylation, acting on the native transcript, cooperate on one gene to obtain full cancer-associated silencing." (PMID 25256425, 2014). "CCLE data showed that CA19-9-high cancer cell lines had significantly upregulated FUT3 (q = 0.003), B3GALT5 (q = 0.003), and FCSK (q = 0.003) mRNA levels compared with CA19-9-normal cell lines." (PMID 41361823, 2025). "In this study, we developed a precisedsiRNA approach to specifically knockdown each of the two isozymesof human β3GalT5 in MCF-7 cells and identified β3GalT5–1as the main isozyme responsible for the synthesis of SSEA-3 (Gb5)from Gb4 in cancer cells." (PMID 40130300, 2025). "In contrast to this ambiguity, the GlycoEnzOnto ontology suggests that the impact of cancer is likely to be more severe on lactosylceramide biosynthesis initiating enzymes: A4GALT5, B3GALT5, B3GNT5 and B4GALT6." (PMID 36282863, 2022). "Among these proteins, we have identified many differentially abundant proteins identified as having a role in cancer (IFIT1, FASTKD2, PIP4K2B, ARID1B, SLC25A33: overexpressed in TR; CALD1, CPA3, B3GALT5, CD177, RIPK1: overexpressed in NR)." (PMID 29681787, 2018). "SKOV3 displayed strong expression of B3GALT5 and very weak expression of B3GALT1 and B3GALT2, consistent with the meta-analysis of the Cancer Cell Line Encyclopedia (CCLE)." (PMID 28167527, 2017). "We have identified many differentially abundant proteins already identified as having a role in cancer, such as the earlier discussed proteins IFIT1, FASTKD2, PIP4K2B, ARID1B and SLC25A33 (more abundant in TR) or CALD1, CPA3, B3GALT5, CD177 and RIPK1 (more abundant in NR)." (PMID 29681787, 2018).
cancer (continued). "Thus, it is possible that the clinical significance of high B3GALT5 expression in adjacent non-tumor part of the cancer tissues might be associated with higher ZEB1 expression and other important but unrevealed role of B3GALT5 in regulation of tumor microenvironment to facilitate tumor progression." (PMID 33413566, 2021). "The overall survival (OS) correlated with the higher AJCC cancer stages III–IV (HR = 2.81, P = 2.5E−04), and higher expression of B3GALT5 in adjacent non-tumor part (HR = 2.63, P = 4.7E−03)." (PMID 33413566, 2021). "Similarly, in multivariate analysis, RFS and OS were both correlated with the higher AJCC cancer stages III–IV (HR = 2.40, P = 7.9E−03, and HR = 3.06, P = 1.0E−04, respectively) and expression of B3GALT5 in adjacent non-tumor tissue (HR = 4.20, P = 5.1E−05, and HR = 2.50, P = 0.02, respectively)." (PMID 33413566, 2021).
tumor (4 papers, 2017 to 2024). "A patient-derived xenograft (PDX) model was used to see the in vivo effects of knockdown of B3GALT5 in BCSCs on tumor growth and metastasis." (PMID 33413566, 2021). "The adverse impacts of high expression of B3GALT5 in non-tumor parts on RFS and OS were found most significant in patients with early stage and luminal A and B subtypes (P = 9.5E−04 and P = 5.4E−04, for RFS and OS, respectively)." (PMID 33413566, 2021). "Knockdown of B3GALT5 significantly suppressed tumor growth rate and decreased tumor size compared to si-Control." (PMID 33413566, 2021). "As to the adjacent non-tumor tissue, we found more significantly higher B3GALT5 mRNA levels in TNBC subtype than the other three subtypes (P = 0.002 vs HER-2-positive subtype; P = 0.024 vs luminal A subtype; P = 0.003 vs luminal B subtype)." (PMID 33413566, 2021). "In vivo studies showed B3GALT5 expression in BCSCs is critical for not only tumor growth but also lymph node and lung metastasis in PDX mice." (PMID 33413566, 2021). "In the tumor tissue, B3GALT5 mRNA levels were significantly higher in the luminal B subtype (P = 0.035) and TNBC subtype (P = 0.001) than the HER-2-positive subtype." (PMID 33413566, 2021). "Knockdown of B3GALT5 in BCSCs AS-B634 significantly retarded tumor growth and reduced metastasis." (PMID 33413566, 2021). "Besides FUT1, we also showed high expression of B3GALT5 in HCC tissues to be associated with advanced TNM stage, metastasis, vascular invasion and tumor recurrence." (PMID 28883415, 2017). "Thus, it is possible that high expression of B3GALT5 might promote tumor metastasis through SLea and other glycans in HCC tissue." (PMID 28883415, 2017). "We examined the mRNA expression levels of the FUT1, FUT2, B3GALT5 and ST3GAL2 in tumor specimens of 135 HCC patients by qRT-PCR." (PMID 28883415, 2017). "The results indicate that relapse-free survival (RFS) correlated with age greater than 45 years (HR = 2.90, P = 0.02), and the higher expression of B3GALT5 in adjacent non-tumor parts (HR = 5.08, P = 1.7E−07) and tumor part (HR = 2.54, P = 3.8E−03)." (PMID 33413566, 2021). "In addition, in tumor tissue of TNBC patients, high expression of B3GALT5 had adverse impact on RFS (P = 0.004) but not OS." (PMID 33413566, 2021).
metabolic disorders (1 paper, 2024). "Furthermore, B3galt5 deficiency abolishes the beneficial effect of intestinal PXR activation on metabolic disorders." (PMID 39004626, 2024). "Since B3galt5 shows a potential role in metabolic diseases, we generated B3galt5 whole-body knockout (B3galt5 −/−) mice by CRISPR-Cas9-mediated gene targeting." (PMID 39004626, 2024). "Furthermore, we showed that B3galt5 is required for the beneficial effects of intestinal PXR activation on HFD-induced metabolic disorders." (PMID 39004626, 2024). "To investigate whether B3galt5 is involved in the pathogenesis of metabolic diseases, we first measured its expression in the intestine of mice with metabolic disorders." (PMID 39004626, 2024). "In our study, we found B3galt5 appeared to be downregulated in the metabolic disorder progression." (PMID 39004626, 2024). "In addition, B3galt5 is highly expressed in colon, and intestinal-specific B3galt5 ablation mice also displayed worse metabolic disorders as well as intestinal barrier integrity with an HFD." (PMID 39004626, 2024). "To test the hypothesis that enhanced activation of intestinal PXR playing a protective role in metabolic disorders is B3galt5-dependent, we administrated B3galt5 knockout mice with TBC." (PMID 39004626, 2024). "Thus, our data suggest that B3galt5 is compromised in both obese mouse models and patients, possibly playing an important role in metabolic diseases as a downstream regulator of PXR." (PMID 39004626, 2024). "Given that B3galt5 was highly expressed in colon, to further confirm the intestinal B3galt5 function influencing metabolic disorders, we generated intestinal epithelial cell-specific B3galt5 knockout mice (B3galt5△IEC) by intercrossing B3galt5f/f mice with Villin-Cre-ERT mice." (PMID 39004626, 2024).
B3GALT5 also shares sentences with these, for which no sentence is quoted: colorectal adenocarcinoma (1 paper); E. coli infection (1); liver cirrhosis (1); nonalcoholic steatohepatitis (1); pancreatitis (1); renal carcinoma (1); virus infection (1).